ISG15 (ISG15 ubiquitin like modifier)
Diseases named in the same sentence as ISG15 in open-access papers (continued):
Sharing a sentence is not in itself a finding about the gene and the disease.
cancer (continued). "However, immunohistochemical staining revealed expression of ISG15 protein in both cancer cells and stromal immune cells." (PMID 16641915, 2006). "Interestingly, a significant fraction of ISG15 protein was localised to the nuclei of cancer cells, whereas ISG15 protein exhibited a diffuse cytoplasmic staining pattern in ISG15-positive stromal cells." (PMID 16641915, 2006). "Indeed, immunohistochemical staining showed ISG15 expression in both cancer cells and stromal immune cells." (PMID 16641915, 2006). "Additionally, ISG15 could serve as a potential target for cancer vaccines, such as the ISG15-based Listeria vaccine, which has demonstrated good immunogenicity in CRC immunotherapy." (PMID 41193953, 2025). "Besides promoting cancer progression, ISG15 and ISGylation also contribute to therapy resistance, serving as key mediators for resistance to chemotherapy and radiation therapy, particularly through their roles in the IFN-related DNA damage resistance signature (IRDS)." (PMID 40103488, 2025). "Likewise, free ISG15 interactions contribute to the metabolic fitness of cancer cells." (PMID 41193953, 2025). "Our pan-cancer pathway analyses reveal that ISG15 significantly and positively correlated to differentiation, inflammation, proliferation, metastasis, and angiogenesis, and negatively correlated with DNA repair, which may provide a general direction for future research." (PMID 40208307, 2025). "ISG15, through its role in immune infiltration and modulation, may address these limitations by offering a broader and more precise predictive capability for immunotherapy responses across diverse cancers." (PMID 40208307, 2025). "Importantly, given its role in enhancing the growth and invasion of several different cancers, circulating ISG15 may represent both a crucial biomarker and target for therapeutic intervention in different cancers." (PMID 40719862, 2025). "Thus, free ISG15 may have differential and beneficial effects on cancer progression as compared to ISGylation, raising the possibility that selectively targeting ISGylation, while preserving or enhancing free ISG15 levels, may be of preventative value." (PMID 39159817, 2024). "The IFN-induced ISG15 protein controls a plethora of cellular pathways, such as DNA damage response, regulation of DNA replication synthesis and stress, intracellular trafficking, modulation of cytoskeleton dynamics, autophagy, host antiviral response, and cancer occurrence and progression." (PMID 38400136, 2024). "Furthermore, the biological activity of ISG15 has been found to vary across different cancer types." (PMID 38951255, 2024). "Thus, targeting ISG15 or ISGylation may be an unexplored approach to restore immune response in patients with cancer." (PMID 38781019, 2024). "Furthermore, some available data suggest that intracellular ISG15 conjugates and free ISG15 could harm patients by stabilizing cellular proteins that promote cancer, and secreted free ISG15 may benefit patients by modulating immune system functions." (PMID 36771004, 2023).
cancer (continued). "However, the literature is mixed as to whether ISG15 has protective or adverse effects during cancer, likely because ISG15 is able to modify a vast number of proteins, resulting in opposing effects depending on context." (PMID 36435199, 2023). "In any case, ISG15 may be considered in the future as a small molecule immunoadjuvant to better inhibit cancer progression in patients who are not susceptible to immunosuppressive therapy." (PMID 37217923, 2023). "However, this might indicate that ISG15 pro-tumoral functions are heterogeneous and depend on the cancer type." (PMID 35864381, 2022). "Whether the heterogeneous expression of ISG15 conjugates is due to the differential expression of ISG15-conjugating/deconjugating enzymes or mutations in ISG15 protein in human cancers is not known." (PMID 35159348, 2022). "Thus, it is very clear that ISG15 gene/protein expression is elevated in most cancers." (PMID 35159348, 2022). "However, completely opposite effects were observed in oesopharyngeal cancer cells, where siRNA-mediated depletion of ISG15 or treatment with cytotoxic drugs (5-Fu and rapamycin), resulted in an increase in endogenous autophagy and an enhancement of drug-resistant cancer cells." (PMID 33718235, 2021). "Although both viruses and cancer can induce the secretion of type I IFNs, whether patterns of enhanced ISG15 expression and ISGylation in cancer cells represent cellular responses to cancer or are merely by-products of cellular processes that have been altered by tumorigenesis is unclear." (PMID 27626310, 2016). "However, ISG15 is probably a double-edged sword in carcinogenesis and cancer suppression." (PMID 27659523, 2016). "Based on this report and our current study, we hypothesize that free ISG15 protein, which is designed to help the immune system to protect the body against viruses and bacteria, may also aid immune cells in detecting cancer cells for their elimination in the human body." (PMID 25749047, 2015). "Thus, ISG15 exists in both free and conjugated pools within cells, both of which are often elevated in cancer, although the basis for differences in cellular levels among different tumors remains unclear." (PMID 25749047, 2015). "Therefore, whether the ISG15 pathway which is highly elevated in most cancers, is a friend or foe during tumorigenesis in vivo is unclear." (PMID 25749047, 2015). "We propose that ISG15 silencing stabilizes HMGCR protein, likely by impeding ubiquitin-proteasomal degradation, thereby elevating cholesterol biosynthesis to sustain cancer cell survival." (PMID 41366470, 2025). "Interferon-stimulated gene 15 (ISG15) correlated significantly with the proliferation and malignancy of the ATC cancer stem cells." (PMID 40271195, 2025). "Our transcriptomic analyses of CM-treated HOSEs uncovered gene-expression profiles defining responses to cancer-like TME, highlighted by STAT1, ISG15, and OAS1 in HOSE1C and ITGA2, GREM1, and CDH13 in HOSE2C." (PMID 39634630, 2024). "We then plotted the expression profile of the top four upregulated ISGs (IFIT2, ISG15, IFIT1 and IFIT3) among various cancer types from the TCGA database." (PMID 38926796, 2024). "The effect and mechanism of ISG15 and KPNA2 on cancer stem cell-like characteristics of ATC cells were determined by molecular biology experiments." (PMID 37501099, 2023). "The ISG15 levels in human CRC were analyzed using the publicly available data from the Human Protein Atlas, The Cancer Genome Atlas, and The University of Alabama at Birmingham, Comprehensive Cancer Center (UALCAN)." (PMID 36831577, 2023). "In this study, we found that ISG15-mediated ISGylation of KPNA2 inhibited its ubiquitination degradation, thereby promoting nuclear translocation of c-MYC and maintaining cancer stem-like characteristics in ATC." (PMID 37501099, 2023).
cancer (continued). "Our studies not only provided new insights into potential intervention strategies targeting ATC CSCs, but also uncovered the novel biological functions and mechanisms of ISG15 and ISGylation for maintaining ATC cancer stem cell-like characteristics." (PMID 37501099, 2023). "Taken together, our results identify the IFNβ/ISG15 pathway as a key modulator of DNA replication fork protection and help explain the complex role of type I IFN—and ISG15 itself—in cancer development and drug response." (PMID 37783689, 2023). "Cancer stem cells with increased expression of IFIT1, IFIT2, IFIT3, and ISG15 were uniquely present in HGSOC and MMMT tumors." (PMID 38328306, 2023). "On the other hand, the expression levels of ISG15, IFI27, OASL, ISG20, and DDX58 were lower in CDDP-R cancer cells than in parent cancer cells, which were consistent with the transcriptome profiling data." (PMID 37174688, 2023). "The RT-qPCR results confirmed that the expressions of ISG15, IFI27, and OASL increased significantly in KU55933-treated CDDP-R and parent cancer cells." (PMID 37174688, 2023). "Among epithelial cells, we identified the EP3 sub-cluster as cancer stem cells, based on high expression of IFIT1 and ISG15." (PMID 38328306, 2023). "Mechanistically, ISG15 mediated the ISGylation of KPNA2 and impeded its ubiquitination to promote stability, further maintaining cancer stem cell-like characteristics." (PMID 37501099, 2023). "In the context of cancer, KO of IFITM1/3 impairs the protein synthesis of a group of molecules induced by IFNγ including HLA-B and ISG15." (PMID 36435199, 2023). "Cluster 0 expressed many interferon-induced genes, such as ISG15, IRF1, ISG20, and more, which play a major role in the development and metastatic progression of cancers." (PMID 37158921, 2023). "The results showed that high expressions of ISG15, IFI27, OASL, CCL5, ISG20, IFIT3, and other 21 ISGs were significantly correlated with improved OS rates in cancer patients receiving ICB therapy." (PMID 37174688, 2023). "In this study, the transcriptomic results showed that oncoVV-AVL significantly downregulated the transcription of ISG15, indicating oncoVV harboring AVL suppressed the antiviral response of the cancer cells to promote viral replication." (PMID 35736181, 2022). "In particular, the expression levels of genes, such as IFI6, MX1, IFIT1, IFIT3, ISG15, OAS1, and OAS2, which belong to the cancer-promoting ISG subset IRDS, were markedly increased." (PMID 35618021, 2022). "Consistent with the findings in human cancer cell lines, the canonical IFN signaling genes such as Isg15, Ifi44, Ifit3, and Ddx58 were induced at a significantly higher magnitude in Rad21-knockdown cells upon IFN-β stimulation." (PMID 36201246, 2022). "ISG15+ and C1QC+ macrophages also mobilized signaling cascades related to carcinoma and T cell exhaustion respectively." (PMID 36439171, 2022). "Drug sensitivity significantly increases after the downregulation of ISG15 and UBE2L642, possibly indicating the potential of these genes as targets for cancer research." (PMID 30013139, 2018). "Both ISG15 and USP18 are deregulated in different cancers, consistent with an important functional role for this DUB in homeostasis of growth-regulatory proteins." (PMID 27980214, 2017). "In the present study, we found that ISG15 and its deISGylase USP18 were induced by anti-cancer agents, and each alone induces cancer cell apoptosis." (PMID 27659523, 2016). "In the present study, we found that ISG15 was induced by anti-cancer agents clioquinol (CLQ) and mefloquinine (MFQ), and more importantly, ISG15 is able to trigger cancer cell apoptosis by modulating the NF-κB signlaing transduction." (PMID 27659523, 2016). "As demonstrated in the present study, both ISG15 and the deIGSlyation enzyme USP18 are upregulated by anti-cancer agents CLQ and MFQ." (PMID 27659523, 2016).
cancer (continued). "Importantly, specific representatives of the residual signature genes (ISG15, IFI27, IFI6, RSAD2) appear to aid cancer cells in evading immunosurveillance and inflammatory cells by inhibiting apoptotic processes." (PMID 40312750, 2025). "In addition to free ISG15, ISGylation is involved in the regulation of DDR in cancer cells to affect drug response." (PMID 41193953, 2025). "Notably, in the TCGA pan‐cancer database, samples exhibiting low KDM4B expression displayed elevated levels of IFN‐β, CXCL10, ISG15, PD‐L1 and PD‐1, in contrast to those with high KDM4B expression." (PMID 38390756, 2024). "Further analyses of RNA sequencing (RNA-Seq) data from 1404 cancer cell lines across 28 cancer types and proteomic data from 375 cancer cell lines across 21 cancer types from the CCLE database revealed similar mRNAs and protein expression levels of ISG15 and SIRT1 in various cancer cell lines." (PMID 38443596, 2024). "Moreover, we observed a similar effect of JIB‐04 on the expression of the downstream signalling genes (Cxcl10, Isg15 and antigen presentation‐related genes) of IFN‐β in both human and mouse cancer cells." (PMID 38390756, 2024). "Given that the contributions of ISG15 and SIRT1 to cancer pathogenesis are complex and remain elusive, we analyzed the mRNA and protein expression levels of ISG15 and SIRT1 in The Cancer Genome Atlas (TCGA) and the Cancer Cell Line Encyclopedia (CCLE) database." (PMID 38443596, 2024). "Several independent studies had indicated that a novel role for ISG15 in cancer stem cell-like characteristics, regardless of its antiviral effect." (PMID 37501099, 2023). "As previously developed tumor-associated antigen (TAA)-based cancer vaccines for CRC are not demonstrating promising results, we propose that interferon-stimulated gene 15 (ISG15) is a novel TAA and therapeutic target for CRC." (PMID 36831577, 2023). "The immune histochemical sections of the HPA database showed that the protein expression of SLPI, DES, IAPP, NPY, ISG15 and HLA-DMB in normal tissue was higher than that in cancer tissue, while the protein expression of PLA2G2A in normal tissue was lower than that in cancer tissue." (PMID 36774376, 2023). "The role of ISG15 and ISGylation in the DDR has mostly been studied in the context of cancer." (PMID 37025175, 2023). "Moreover, it is important to consider that ISGylation levels are related to the deregulation of ISG15, ISGylation system enzymes, and USP18 de-ISGylase expression in cancer." (PMID 37711589, 2023). "Strategies to increase systemic levels of free ISG15 by targeting UBE1L and UBCH8 may therefore be beneficial for cancer patients." (PMID 35159348, 2022). "MUC1-C-induced ISG15 expression thus expands the inextricable links among intrinsic activation of the type I IFN pathway, DNA damage resistance and chronic inflammation in cancer cells." (PMID 35681561, 2022). "Intracellular levels of free ISG15 are expected to increase due to decreased ISGylation (due to low levels of UBE1L) and increased ISG15 deconjugation (due to high levels of USP18) of cellular proteins in these cancer tissues." (PMID 35159348, 2022). "Therefore, not only elucidating the mechanisms by which ISG15 and ISGylation modulate sensitivity or resistance to therapies but also investigating the possibility that ISG15 and ISGylation can serve as indicators for the selection of therapy could be promising for improving cancer patient survival." (PMID 36319753, 2022). "Pan‐cancer analysis using starBase v3.0 project observed negative correlation between ISG15 and KLF12 in multiple cancers." (PMID 33797839, 2021). "More importantly, ISG15 and USP18 induced cancer cell apoptosis." (PMID 27659523, 2016).
cancer (continued). "However, we found that ISG15 and de-ISGylase USP18 were induced by several anti-cancer agents, which was confirmed by both RT-PCR and immunoblotting assays." (PMID 27659523, 2016). "This discrepancy presents a hurdle for preclinical studies, and the result is that murine models may not fully reflect the effects of ISG15 on human cancers." (PMID 41193953, 2025). "Combined with the Ub-based DUB activity profiling data, the ISG15-based activity profiling of deISGylases and USP18 will help comprehensively investigate and define the activity-related landscape of Ubl proteases and unravel important Ub and Ubl-dependent biological processes in cancer." (PMID 39843430, 2025). "However, the mechanistic consequences of ISGylation in cancer have not been fully elucidated, largely due to a lack of knowledge on the ISG15 target repertoire." (PMID 38443596, 2024). "Moreover, it was unclear whether such the stemness regulatory function of ISG15 also exhibited in ATC cells, especially in its cancer stem cells." (PMID 37501099, 2023). "However, due to the limitations of current research, the regulation of ISG15/ISGylation on cancer progression is not completely clear, thus further comprehensive and sufficient correlation studies are still needed." (PMID 36771004, 2023). "USP18, an IFN-stimulated gene 15 (ISG15) DUB, which contains α-helical thumb domain at the N-terminus, the C-terminal palm domain, and the finger domain, has been reported to occupy essential position in various physiological and pathophysiological processes, especially in cancers." (PMID 36582601, 2022). "Moreover, ISG15 abolishes TNF-α-activated NF-κB signaling and decreases the transcription of NF-κB-modulated genes including XIAP and Mcl-1, two oncogenes in various cancers." (PMID 27659523, 2016). "Therefore, we investigated whether overexpressed ISG15 had an effect on IFN-α resistance and possibly enhanced cancer cell apoptosis by upregulating protein ubiquitination." (PMID 24024201, 2013). "Notably, ISG15 expression is significantly higher in transcriptional expression in tumors exhibiting a gain of ISG15, relative to those without change in some cancer types, suggesting that the gain of ISG15 orchestrates the subsequent elevation in ISG15 expression." (PMID 40208307, 2025). "Finally, to elucidate whether the prognostic impact of ISG15 expression is independent of clinical factors, we conducted univariate and multivariate Cox regression analyses focusing on OS across five types of cancer wherein ISG15 has a demonstrable effect on prognostic outcomes." (PMID 40208307, 2025). "In this context, chronic DAMP-induced PRR/STING activation leads to persistent low-dose IFN-β autocrine and paracrine stimulation of cancer cells, which induces UISGF3-mediated transcription of the non-canonical pathway that overlaps with the IRDS (STAT1, ISG15) and includes RIG-I and MDA5." (PMID 35681561, 2022).